FBXL16 (F-box and leucine rich repeat protein 16)
Description:
Substrate-recognition component of the SCF (SKP1-CUL1-F-box protein)-type E3 ubiquitin ligase complex.
Synonyms: C16orf22; FBL16; MGC33974; c380A1.1
Tractability: PROTAC: its protein half-life has been measured.
Gene: Protein-coding gene on chromosome 16 (692,498 to 705,843, reverse strand). Ensembl gene ENSG00000127585.
Pathways (Reactome):
Immune System: Antigen processing: Ubiquitination & Proteasome degradation
Metabolism of proteins: Neddylation
Gene Ontology:
Molecular function: protein binding
Biological process: SCF-dependent proteasomal ubiquitin-dependent protein catabolic process
Cellular component: cytosol; cytoplasm
Genetic constraint (gnomAD): Loss-of-function variants: 7 observed, 24.15 expected, observed/expected ratio (o/e) 0.29, 90% interval 0.16 to 0.54. The synonymous counts are far from expectation, so gnomAD's model fits this gene poorly and the ratio says little. Missense variants: 462 observed, 539.52 expected, observed/expected ratio (o/e) 0.86, 90% interval 0.79 to 0.93. Synonymous variants: 355 observed, 263.23 expected, observed/expected ratio (o/e) 1.35, 90% interval 1.24 to 1.47.
Homologues: Orthologues: chimpanzee FBXL16 (99% identical), macaque FBXL16 (99% identical), dog FBXL16 (98% identical), guinea pig FBXL16 (97% identical), rat Fbxl16 (97% identical), mouse Fbxl16 (96% identical), pig FBXL16 (95% identical), tropical clawed frog fbxl16 (81% identical), zebrafish fbxl16 (79% identical), Drosophila melanogaster CG32085 (51% identical), Caenorhabditis elegans skpt-1 (14% identical), Caenorhabditis elegans gadr-5 (13% identical), and 13 more. Paralogues in human: FBXL20 (19% identical), FBXL2 (19% identical), FBXL7 (19% identical), FBXL17 (18% identical), FBXL4 (16% identical), FBXL14 (16% identical), FBXL5 (16% identical), FBXL6 (16% identical), FBXL13 (15% identical), FBXL19 (15% identical), FBXL18 (15% identical), SKP2 (13% identical), and 3 more.
Diseases named in the same sentence as FBXL16 in open-access papers:
FBXL16 is named in the same sentence as 14 diseases in open-access papers, as found by Europe PMC text mining. Sharing a sentence is not in itself a finding about the gene and the disease. The quoted sentences say what the papers report.
Cognitive impairment (1 paper, 2024). Abnormal cognition is characterized by deficits in thinking, reasoning, or remembering. "Interestingly, compared with the control mice, FBXL16-cko mice with Aβ overexpression, which were induced via stereotaxic injection, presented more severe cognitive impairment in water maze and Y maze tests." (PMID 39568047, 2024).
endometrial carcinoma (1 paper, 2022). A malignant tumor arising from the epithelium that lines the cavity of the uterine body. "Therefore, the expression profile of FBXL16 in cancer and adjacent tissues of endometrial cancer associated with estrogen resistance was further investigated by RT-PCR." (PMID 36106050, 2022). "Based on the TCGA database, FBXL16 presented a high expression level in 174 cases of Uterine Corpus Endometrial Carcinoma (UCEC) tissues relative to 91 cases of normal tissues." (PMID 36106050, 2022). "Clinical samples were collected for determining the correlation between FBXL16 and endometrial carcinoma." (PMID 36106050, 2022). "It implied that the expression of FBXL16 in normal tissues and endometrial cancer tissues was significantly different." (PMID 36106050, 2022). "MPA tolerance of endometrial cancer cells was inhibited by knockdown of FBXL16 in DNA content assessment, CCK-8, and colony formation." (PMID 36106050, 2022). "All these data revealed a positive association of FBXL16 in cell cycle regulation and tumor proliferation promotion in MPA-resistant endometrial cancer cell, Ishikawa/MPA." (PMID 36106050, 2022). "Although the F-box proteins have been recognized to play an important role in cell proliferation and tumor generation, the function of FBXL16 in endometrial carcinoma is virtually unknown." (PMID 36106050, 2022). "Moreover, the immunohistochemical results showed the highly positive correlation between Ki67 and FBXL16, implying the oncogenic role of FBXL16 in endometrial carcinoma." (PMID 36106050, 2022). "However, there are few studies on F-box and leucine-rich repeat protein 16 (FBXL16) in endometrial carcinoma." (PMID 36106050, 2022). "Inhibiting the expression of FBXL16 may be new direction for progesterone treatment resistance in endometrial carcinoma." (PMID 36106050, 2022). "FBXL16 was upregulated in endometrial carcinoma tissues and many kinds of endometrial cell lines." (PMID 36106050, 2022). "The abnormal expression of FBXL16 facilitated the MPA resistance of endometrial cancer by stabling the cyclin D1 protein; however, the proteasome-dependent degradation of cyclin D1 recognized by ubiquitinated E3 ligase was not the only one mechanism of MPA resistance." (PMID 36106050, 2022). "In our experiment, FBXL16 was demonstrated to enhance MPA resistance in endometrial cancer cells." (PMID 36106050, 2022). "Further study on transcription profiling or protein profiling of FBXL16 overexpression or knockdown in endometrial cancer cells could be expected in the future." (PMID 36106050, 2022). "In summary, our results demonstrated that FBXL16 promoted MPA resistance of Ishikawa cell by PP2AB55α interaction and AKT1/GSK3β/cyclin D1 pathway in endometrial carcinoma, while knockdown of FBXL16 can reverse the MPA resistance of Ishikawa." (PMID 36106050, 2022). "Our work revealed that the abnormal expression of FBXL16 in Ishikawa cells led to the inhibition of GSK3β-dependent cyclin D1 degradation and ultimately the promotion of MPA resistance in endometrial carcinoma." (PMID 36106050, 2022). "The high expression of FBXL16 was positively correlated with MPA resistance and poor prognosis of endometrial cancer." (PMID 36106050, 2022). "Furthermore, FBXL16 promoted the MPA resistance of Ishikawa cells by interacting with PP2AB55α and enhancing the stability of cyclin D1 in endometrial carcinoma." (PMID 36106050, 2022). "Finally, to further explore the role of FBXL16 in proliferation and MPA-resistance of endometrial cancer in vivo, tumor bearing model on nude balb/C mice was established." (PMID 36106050, 2022).
memory impairment (1 paper, 2024). "By regulating different factors in the APP metabolic pathway, our study confirmed the role of FBXL16 in improving cognitive and memory impairments in AD." (PMID 39568047, 2024).
metastatic tumors (1 paper, 2021). "DIRAS1, FBXL16, TP53I11, TFF2, and ZNF467 were upregulated in both metastatic tumors and GHSROS-overexpressing PC3 and LNCaP cells, while AASS, CHRDL1, CNTN1, IFI16, and MUM1L1 were downregulated." (PMID 33585078, 2021).
mucinous adenocarcinoma (1 paper, 2024). An invasive adenocarcinoma composed of malignant glandular cells which contain intracytoplasmic mucin. "Significant results (P< 0.05) included associations with WNT11 and FBXL16 and body mass index (BMI), MSLN and mucinous adenocarcinoma, and SLC38A11 and metastasis." (PMID 38680862, 2024).
ovarian carcinoma (1 paper, 2021). A malignant neoplasm originating from the surface ovarian epithelium. "In these differentially expressed FBPs, FBXL16 is the highest expressed FBP in ovarian cancer tissues, followed by FBXO16." (PMID 34333526, 2021).
cancer (4 papers, 2022 to 2025). A tumor composed of atypical neoplastic, often pleomorphic cells that invade other tissues. "While F-box family members like FBXL16 predominantly regulate proteasome-dependent processes in cancers, the FBXO10–FRMPD1 axis defines a unique oncogenic pathway in hepatic malignancies." (PMID 40699790, 2025). "While FBXL16 is an oncoprotein that promotes cancer cell growth and migration by increasing c-MYC stability, Orientia evolved as an obligate intracellular microbe to stabilize c-MYC and extend the life of its host cell." (PMID 39976440, 2025). "The carcinoma tissues and pare-carcinoma tissues were furtherly conducted immunohistochemistry (IHC) to show the expression of FBXL16." (PMID 36106050, 2022). "Interestingly, the protein encoded by the best-associated gene, FBXL16, stabilizes C-MYC by blocking its ubiquitination and promotes cancer cell proliferation and migration." (PMID 37730697, 2023).
tumor (2 papers, 2020 to 2022). "FBXL16 could promote cell proliferation and accelerate the G1-phase, which contributed to tumor generation in nude mice." (PMID 36106050, 2022). "We found that the mRNA levels of some F-box proteins were significantly increased in HCC samples when compared with non-tumor tissues, including FBXL18, FBXL16 and FBXL6." (PMID 32576198, 2020).
FBXL16 also shares sentences with these, for which no sentence is quoted: allergic asthma (1 paper); allergic disease (1); Alzheimer disease (1); asthma (1); breast carcinoma (1); lung adenocarcinoma (1).